IL10 (interleukin 10)
Diseases named in the same sentence as IL10 in open-access papers (continued):
Sharing a sentence is not in itself a finding about the gene and the disease.
asthma (continued). "Herein we used wild-type (w.t.)and CD40-/- DC10 to assess the role of CD40 in DC10 reversal of the asthma phenotype in OVA-asthmatic mice, complementing IL-10 expression in the CD40-/- DC to assess whether IL-10 supplementation can over-ride a lack of CD40 signaling in these cells." (PMID 33793599, 2021). "The expression of miRNA-221-5p was increased in model of asthma, compared with negative group The vitro model of asthma treated with miRNA-221-5p mimic resulted in the reduction of IL-6, IL-17, IL-21 and IL-22 levels, and induction of IL-10, IL-35 and TGF-β levels." (PMID 34863307, 2021). "Our results obtained from a cohort of patients with allergic rhinitis with and without asthma treated in the real-world setting provide evidence of increased levels of DP-sIgG4, Der p 1 sIgE, and IL-10 as mechanisms of immune tolerance induced by AIT specific for HDMs." (PMID 34178239, 2021). "However, the observed increase in serum IL-10 in our study together with the negative correlation between BMI and H3cit in asthma subjects make further research of interactions between cytokines, adiponectin and ETs release of interest." (PMID 32685129, 2020). "In addition, DClps produced more IL-10 and TGF-β than DCim, leading to dramatic decreases in the phosphorylation of both STAT4 and STAT6, which are critical in initiating Th1- and Th2-mediated immunoinflammatory processes in asthma, respectively." (PMID 32807859, 2020). "Dexa increased the level of IL-10 compared to the asthma group (P < 0.01), but MYR could not increase its level." (PMID 32641957, 2019). "The frequency of Foxp3+IL-10+ CD4+ T cells did not correlate with asthma severity (data not shown)." (PMID 29507584, 2018). "The role of IL-10 in asthma pathogenesis has not been well documented." (PMID 30915130, 2018). "Since attenuated production of intracellular IL-17A and IL-10 in mononuclear cells from patients with severe asthma could not be explained by progression of asthma stages, we decided to investigate if the expression levels of IL-10 and IL-17A are correlated." (PMID 30915130, 2018). "Similar to our previous study showing that bvPLA2 was effective in decreasing Th2 cytokine expression in an asthma mouse model, treatment of WT mice with bvPLA2 following DFE/DNCB exposure significantly decreased the expression of Th1 and Th2 cytokines including IFN-γ, IL-4, IL-6, and IL-10." (PMID 29614845, 2018). "Cytokines including interleukin 4 (IL-4), interleukin 5 (IL-5), IL-6, IL-8, interleukin 10 (IL-10), monocyte chemoattractant protein (MCP)-1/CCL2, and thymus and activation-regulated chemokine (TARC)/CCL17 trigger secondary inflammatory events, aggravating asthma pathogenesis." (PMID 29755573, 2018). "Consistently, we found that the IL-10 expression level is not correlated to the severity of asthma and other factors may be contributing." (PMID 30915130, 2018). "The absence of changes in IFN-γ and IL-10 may be related to the timing of analysis (7 days after the last challenge), since such modifications have been described during asthma resolution." (PMID 28646903, 2017). "Other studies have suggested that TGF-β, rather than IL-10, may be more important and serve as a biomarker of asthma control in atopic asthma." (PMID 28725641, 2017). "Previously in this cohort, the IL10 rs1800896 A/A genotype was associated with non-RSV aetiology of bronchiolitis, and under the age of seven, the G/G genotype was protective for post-bronchiolitis asthma." (PMID 26473365, 2015). "In contrast, regulatory T cells (Treg cells, a CD4+CD25+FOXP3+ subset) have inhibitory effects on asthma airway inflammation, inhibiting the proliferation of other T cells; it is believed they are mediated by cytokines such as tumor growth factor beta (TGF-β) and IL-10." (PMID 26565810, 2015). "However, the interactions between IL-10 and innate IFNs during virus-induced exacerbations of asthma have not been well studied." (PMID 25430775, 2015).
asthma (continued). "It has been showed that the IL-10 level in both asthmatic group and alleviated group was lower than control group, while another study reported that the IL-10 level in asthmatic children without a family history of asthma was comparable with that in healthy control group." (PMID 23717481, 2013). "Nevertheless, the observed suppression of asthma manifestations was independent of IL-10 or TGFβ, indicating a lack of involvement of antigen-specific Tregs that can be explained by the distant anatomical location of OVA (intranasal) and Pam3Cys (intraperitoneal) administration." (PMID 23393567, 2013). "However, we did not observe any effect of H89 on IL-10 expression in BAL fluid from OVA sensitized/challenged mice in the two asthma models we used (data not shown)." (PMID 23189147, 2012). "Immunotherapy is used to manage IgE mediated rhinitis and asthma by down-regulation of the Th2 response by promoting a Th1 response due to production of interferon (IFN) γ, IL-2 and IL-12 and up-regulation of regulatory T lymphocytes, producing IL-10 and transforming growth factor (TGF) β." (PMID 19900263, 2009). "Importantly, only KLRG1 was associated with the sex disparities, and whether the KLRG1+ILC2 cells produce IL-10 and the association of IL-10+KLRG1+ILC2 and sex differences in asthma has not yet been investigated." (PMID 37947634, 2023). "The serum levels of interleukin (IL)-8, IL-10, and IL-18 were examined using ELISA kits in 34 patients with M. pneumoniae infection (Group 1, 11 with severe mycoplasmal pneumonia; Group 2, 13 with mild mycoplasmal pneumonia; Group 3, 10 with asthma) and 32 age-matched, non-infected controls." (PMID 26751073, 2016). "In our study, we could not find any differences regarding IL-10 production by T cells between children with asthma and healthy controls, which is in line with the findings from other studies, but a trend towards higher cytokine level in the CD4+ T in children with severe asthma was observed." (PMID 21197090, 2010). "Both groups including obese children showed higher leptin and IL-10 levels and lower adiponectin and TNF-alpha levels compared to children with no obesity and asthma." (PMID 36291398, 2022). "Down-regulation of miRNA-221-5p increased the levels of IL-6, IL-17, IL-21 and IL-22, and reduced those of IL-10, IL-35 and TGF-β in in vitro model of asthma, compared with negative group." (PMID 34863307, 2021). "In a recent work, new gene and protein biomarkers CHI3L1, IL-8, IL-10, MSR1, PHLDA1, PI3, and SERPINB2, were proposed to discriminate healthy control subjects from nonallergic asthmatic patients (T2-low) and to measure asthma severity." (PMID 31143187, 2019). "We did not observe a significant difference between asthma and controls with respect to the incidence of other Foxp3 or IL-10 positive cells: CD4+Foxp3+, CD4+Foxp3+CD25+, CD4+IL-10+IL-4- or CD4+Foxp3+IL-10+." (PMID 25132806, 2014). "H. polygyrus-infected IL-10−/− mice were not protected from ovalbumin-induced asthma; however, MLN cells transferred from IL-10−/−H." (PMID 23053394, 2012). "For other asthma-relevant genes such as TNF, IL-4, IL-10, CCL12 (MCP-5), CCL5 (RANTES), and CCR3, there were no significant IL-13-inducible or statin effects on gene expression." (PMID 22583375, 2012). "On the other hand an increase in IL-10 and IL-13 in the CD4+, but not in the CD8+ T cells, was related with duration of asthma." (PMID 21197090, 2010). "After establishing the asthma model, the levels of IL-5, IL-13, MCP-1, TNF-α, and eotaxin significantly increased in the PLA group compared with those in the NOR group (P < 0.01), while the IL-10 level significantly decreased by 42.0% (P < 0.01)." (PMID 39820222, 2025). "Moreover, we know that IL-10 expression by DC10 is essential to their abilities to induce tolerance, such that IL-10 knock-out or IL-10-silenced, specific allergen-presenting DC10 have no impact on the disease phenotype in mouse models of asthma." (PMID 33793599, 2021).
asthma (continued). "However, simple exposure to 1 μg LPS without asthma induction (LPS/PBS) did not significantly affect Foxp3, GATA3, or ROR-γt mRNA levels nor IL-10, TGF-β, IL-4, IL-5, IL-13, or IL-17 levels (p > 0.05) compared to those of Control mice." (PMID 33072079, 2020). "The results suggest that treatment of asthma patients with SIT/CB induces IL-10+ B cells while treatment with either SIT alone induces IgE positive cells, and treated with CB alone does not induce neither IL-10+ B cells nor IgE positive cells." (PMID 26857726, 2016). "Our data confirm that existing IL-10-dependent mechanisms in atopic patients prone to development of asthma are not sufficient: These patients have lower numbers of CD4+ T cells positive for IL-10R, and in addition, their IL-10 levels drop following bronchial allergen challenge." (PMID 24865466, 2014). "Another group showed that severe asthma was neither TH1 or TH2, but severe asthma was characterized by elevations in BAL CXCL1 (growth-related oncogene, GRO), RANTES (regulated on activation, normal T cell-expressed and -secreted, CCL5), IL-12, interferon (IFN)-γ and IL-10." (PMID 39596984, 2024). "We tested this hypothesis by comparing plasma cytokines, including IL-2, IL-5, IL-10, IL-13, IL-17A, IL-22, IL-33, IFN-γ, and TNF-α and the adipokine, leptin in normal weight and overweight/obese children, both with and without asthma in a cross-sectional study." (PMID 39902293, 2024). "Under these conditions, CD8-depleted PBMCs from the patients with SR asthma produced significantly increased mean concentrations of both IL-17A and IFN-γ compared with the those seen in the patients with SS asthma, although the mean production of IL-10 and IL-13 did not significantly differ." (PMID 25772594, 2015). "IL-10 release is increased by theophylline and this effect may be mediated via PDE inhibition, although this has not been seen at the low doses that are effective in asthma." (PMID 27713276, 2010).
Obesity (485 papers, 2010 to 2026). Accumulation of substantial excess body fat. "Their main function is to create a homeostatic environment via anti-inflammatory cytokines, such as IL-10, a cytokine demonstrated to regulate obesity-associated metabolic dysfunction." (PMID 40467990, 2025). "Reduced IL-10 levels have been associated with increased adipose tissue macrophage infiltration and sustained low-grade inflammation in obesity." (PMID 40867531, 2025). "Distinct behaviors of IL-10 and IL-6 in relation to obesity underline the necessity of considering individual cytokine profiles when evaluating bariatric surgery outcomes." (PMID 39180618, 2024). "B cell-specific IL-10 deletion aggravates AT inflammation and IR in obese mice, whereas adaptive transfer of AT Bregs ameliorates these effects, supporting a protective role of IL-10-expressing Bregs in obesity-linked inflammation and IR." (PMID 38455510, 2024). "Low IL-10 levels are associated with metabolic syndrome, and obesity is correlated with increased levels of this cytokine." (PMID 38674931, 2024). "Winer38 observed that diet-induced obesity led to a reduction in the expression of Ym1, arginase 1, and Il10 genes, causing a shift in the polarization state of macrophages from an anti-inflammatory M2 state to a proinflammatory M1 state in ATMs." (PMID 38263234, 2024). "IL-10, an anti-inflammatory cytokine, plays a protective role against chronic inflammation associated with obesity." (PMID 39180618, 2024). "The distinct behaviors of IL-10 and IL-6 in relation to obesity underline the necessity of considering individual cytokine profiles when evaluating inflammation and obesity interventions." (PMID 39180618, 2024). "It has been proposed that circulating concentrations of IL-1RA and IL-10 are increased in obese subjects to counterbalance chronic inflammatory states associated with obesity." (PMID 36771387, 2023). "Since obesity reduces IL-10 levels, systemic IL-10 treatment was observed to significantly alleviate LA remodeling and the susceptibility to AF in diet-induced obesity." (PMID 37608837, 2023). "Obesity was associated with an upregulation of the gene expression of the inflammatory markers Mcp-1 (p < 0.01), IL-6 (p < 0.01), IL-10 (p < 0.01) and Tnf-α (p < 0.001), and with an upregulation of the mRNA levels of Nox-1 (p < 0.05) and Ho-1 (p < 0.001)." (PMID 37239868, 2023). "CD4+Foxp3+ regulatory T cells (Tregs) represent a critical source of IL-10, where the loss of IL-10 Treg resulted in increased insulin sensitivity and reduced obesity in mice fed with a high-fat diet." (PMID 36362238, 2022). "Both circulating and WAT-expressed IL-10 are upregulated by obesity in women and WAT IL-10 is strongly linked to IR." (PMID 36313784, 2022). "The presence of obesity was also associated with a lower percentage of IL‐10+CD19+ cells among patients with mild, moderate and, mainly, severe AA." (PMID 35734271, 2022). "Although the associations of IL-10 with obesity and metabolic complications have been studied previously, the regulation of IL-10 in different sexes has, to the best of our knowledge, not been addressed." (PMID 36313784, 2022). "Blimp1 deficiency in Treg cells reduces IL-10+ Treg cells especially within the adipose tissue, and Blimp1 deficient mice are protected from insulin resistance and obesity." (PMID 35359918, 2022). "Many candidate genes and polymorphisms have been considered, including variants of the IL10 genes, involved in inflammatory process and many other mechanisms related to the development of overweight and obesity." (PMID 35205336, 2022). "We also analyzed their association with biomarkers of obesity (adiponectin and leptin) and inflammation (interleukin-6 (IL-6) and interleukin (IL-10))." (PMID 35207221, 2022). "An association of IL10 with obesity is reported mainly in correlation with ATM and inflammatory balance." (PMID 35205336, 2022).
Obesity (continued). "In support, Treg cell specific IL-10 deficiency leads to increased insulin sensitivity and reduced obesity in male mice fed with high fat diet." (PMID 35359918, 2022). "Regarding BMI, obesity was associated with a lower percentage of IL‐10+FoxP3+CD4+ T‐cells only in patients with severe AA when compared to other patients and the control group." (PMID 35734271, 2022). "We next examined if the sex-specific differences in IL-10 regulation by obesity and T2D associated with the levels of circulating hormones linked to the gonadotropin axis (FSH, LH, SHBG, E1 and E2)." (PMID 36313784, 2022). "Altogether, the reported data postulate TetraSOD® as a therapeutic natural ingredient to fight against low-grade inflammatory detrimental effects caused by obesity via upregulation of IL-10." (PMID 36235679, 2022). "The studies report that obesity is associated with significantly elevated levels of Il-5, Il-10, Il-12, Il-13, IFN-γ and TNF-α." (PMID 34444287, 2021). "In this sense, loss of IL10 expression in mice increased energy expenditure and protected against diet-induced obesity." (PMID 34248663, 2021). "Unexpectedly, Treg-specific loss of IL-10 resulted in increased insulin sensitivity and reduced obesity in high-fat diet–fed male mice." (PMID 33351782, 2021). "As mentioned, because it produces oxidative stress and causes inflammatory conditions, obesity is one of the factors that increases the basal levels of IL-6, IL-1β, and fibrinogen and reduces anti-inflammatory markers such as IL-10 and nesfatin-1." (PMID 33997019, 2021). "Together, these results demonstrate that IRF3 restrains obesity-associated macrophage inflammatory activation through IFNβ-induced IL-10." (PMID 34091599, 2021). "The second reason involves inflammatory factor stimulation, as obesity can cause adipose cells to secrete inflammatory factors, such as C-reactive protein, interleukin 6 (IL-6), IL-10, and tumor necrosis factor (TNF-α)." (PMID 35004287, 2021). "Low expression of anti-inflammatory cytokines, such as IL-10 has been associated with obesity and metabolic syndrome." (PMID 33526854, 2021). "In summary, Fas mutation conveys resistance to high-fat diet-induced obesity by increasing IL-4 and IL-10 and by promoting thermogenic protein activity and browning." (PMID 32686763, 2020). "Previous studies have demonstrated that IL-10 is an important protective cytokine against the chronic sustained inflammation commonly associated with aging, obesity, and diabetes mellitus." (PMID 32824387, 2020). "In a transgenic mouse model with muscle-specific IL-10 overexpression, IL-10 reduced insulin resistance and protected skeletal muscle from obesity-associated macrophage infiltration." (PMID 32824387, 2020). "The multinomial regression model revealed a significant association between obesity and IL-10 concentrations, but the significance was lost after the model was adjusted for smoking and periodontal status." (PMID 31817464, 2019). "Lower increases in obesity, adiposity and insulin resistance were found in IL10 deficient than in WT controls after 6 months on an HFD." (PMID 30158466, 2018). "The only significant association found with high IL-10 mRNA expression in HCC tumors was obesity (AOR = 2.34, 95% CI = 1.30–4.23, p = 0.004)." (PMID 30034633, 2018). "We therefore concluded that IL-10/JAK-STAT pathway is associated with obesity-related hypertriglyceridemia, and the pathogenesis mechanism require further study." (PMID 29895283, 2018). "In the present study, we evaluated the adipose and circulating IL-10 levels and their association with the childhood obesity and obesity–related hypertriglyceridemia in both a cross-sectional study of humans and in a rat study." (PMID 29895283, 2018). "To observe the adipose and circulating IL-10 levels and their association with obesity, we established a high-fat diet induced obesity rat model with aggravated lipids disorders, of which serum TG, FFA and TC were increased." (PMID 29895283, 2018).